PRKAR2A (protein kinase cAMP-dependent type II regulatory subunit alpha)
Description:
Regulatory subunit of the cAMP-dependent protein kinases involved in cAMP signaling in cells. Type II regulatory chains mediate membrane association by binding to anchoring proteins, including the MAP2 kinase.
Synonyms: PKR2; PRKAR2
Tractability: Small molecule: a structure with a bound ligand is known. Antibody: UniProt places it where antibodies can reach, with high confidence; its Gene Ontology location is reachable by antibodies, with high confidence. PROTAC: ubiquitination databases record sites on it; its protein half-life has been measured; a small molecule that binds it is known.
Target class: Kinase; Protein kinase regulatory subunit; Enzyme
Gene: Protein-coding gene on chromosome 3 (48,744,591 to 48,847,874, reverse strand). Ensembl gene ENSG00000114302.
Subcellular location: Cytoplasm; Cell membrane
Subcellular location (Human Protein Atlas): Basal body; Centriolar satellite; Mid piece; Cytosol; Vesicles
Pathways (Reactome):
Signal Transduction: DARPP-32 events; GPER1 signaling; Hedgehog 'off' state; PKA activation
Disease: ADORA2B mediated anti-inflammatory cytokines production; FCGR3A-mediated IL10 synthesis
Metabolism: Glucagon-like Peptide-1 (GLP1) regulates insulin secretion; PKA activation in glucagon signalling
Cellular responses to stimuli: High laminar flow shear stress activates signaling by PIEZO1 and PECAM1:CDH5:KDR in endothelial cells
Developmental Biology: ROBO receptors bind AKAP5
Hemostasis: Factors involved in megakaryocyte development and platelet production
Neuronal System: CREB1 phosphorylation through the activation of Adenylate Cyclase
Transport of small molecules: Vasopressin regulates renal water homeostasis via Aquaporins
Gene Ontology:
Molecular function: cAMP-dependent protein kinase inhibitor activity; cAMP-dependent protein kinase regulator activity; protein binding; protein domain specific binding; protein kinase A catalytic subunit binding; ubiquitin protein ligase binding; cAMP binding
Biological process: negative regulation of cAMP/PKA signal transduction; activation of protein kinase A activity; adenylate cyclase-activating G protein-coupled receptor signaling pathway; cellular response to glucagon stimulus; chemical synaptic transmission; intracellular signal transduction; negative regulation of inflammatory response to antigenic stimulus; renal water homeostasis; vascular endothelial cell response to laminar fluid shear stress
Cellular component: axoneme; cAMP-dependent protein kinase complex; centrosome; cytoplasm; cytosol; extracellular exosome; focal adhesion; membrane; nucleotide-activated protein kinase complex; plasma membrane; plasma membrane raft; protein-containing complex; ciliary base; synapse
Genetic constraint (gnomAD): Loss-of-function variants: 18 observed, 35.76 expected, observed/expected ratio (o/e) 0.5, 90% interval 0.35 to 0.75. The upper end of that interval is the gene's LOEUF score, 0.75, which puts it in group 3 of 6, group 1 being the genes least tolerant of losing a copy. Missense variants: 392 observed, 445.42 expected, observed/expected ratio (o/e) 0.88, 90% interval 0.81 to 0.96. Synonymous variants: 161 observed, 169.5 expected, observed/expected ratio (o/e) 0.95, 90% interval 0.83 to 1.08.
Homologues: Orthologues: chimpanzee PRKAR2A (99% identical), macaque PRKAR2A (99% identical), dog PRKAR2A (89% identical), rabbit PRKAR2A (87% identical), mouse Prkar2a (86% identical), pig PRKAR2A (86% identical), guinea pig PRKAR2A (86% identical), rat Prkar2a (85% identical), tropical clawed frog prkar2a (71% identical), zebrafish prkar2aa (69% identical), zebrafish prkar2ab (60% identical), Drosophila melanogaster Pka-R2 (47% identical). Paralogues in human: PRKAR2B (67% identical), PRKAR1B (36% identical), PRKAR1A (36% identical), CNBD1 (17% identical).
Diseases named in the same sentence as PRKAR2A in open-access papers:
PRKAR2A is named in the same sentence as 33 diseases in open-access papers, as found by Europe PMC text mining. Sharing a sentence is not in itself a finding about the gene and the disease. The quoted sentences say what the papers report.
colitis (5 papers, 2021 to 2024). Inflammation of the colon. "In this study, we report a previously unidentified function of PRKAR2A deficiency in ameliorating DSS-induced colitis." (PMID 34349238, 2021). "We observed that PRKAR2A deficiency protected mice from dextran sulfate sodium (DSS)-induced experimental colitis." (PMID 34349238, 2021). "The protection against DSS-induced colitis was due to a deficiency of PRKAR2A in intestinal epithelial cell (IEC)." (PMID 34349238, 2021). "In this study, for the first time, we reported that PRKAR2A deficiency protects mice against DSS-induced experimental colitis by facilitating ISG expression and modulating the gut microbiota." (PMID 34349238, 2021). "Collectively, our data demonstrate that an altered gut microbiota is the primary cause of a lower sensitivity to DSS-induced colitis in Prkar2a−/− mice." (PMID 34349238, 2021). "To further determine the protective effect of Prkar2a deficiency in DSS-induced colitis, we increased the concentration of DSS to 3% and extended the observation time to 14 days." (PMID 34349238, 2021). "Though the tumour‐promoting roles and mechanisms had not been fully elucidated, our findings strongly revealed that human PRKAR2A‐derived circRNAs might shorten the colitis‐to‐carcinoma process and cause a poor prognosis of CAC patients." (PMID 35184406, 2022). "Our data elucidates a function of PRKAR2A deficiency in ameliorating DSS-induced colitis, which was earlier unidentified, thus suggesting that PRKAR2A might contribute to the unsatisfactory results of PDE4 inhibitor in the IBD clinical trial." (PMID 34349238, 2021). "To clarify whether PRKAR2A regulates the development of colitis, we used PRKAR2A-deficient (Prkar2a−/−) mice in this study." (PMID 34349238, 2021). "As PRKAR2A was mainly detected in IECs, we investigated whether the protection against DSS-induced colitis in Prkar2a−/− mice was due to an intrinsic epithelial PRKAR2A deficiency." (PMID 34349238, 2021). "Inhibition of ISGs partially reversed the protective effects against DSS-induced colitis in Prkar2a−/− mice." (PMID 34349238, 2021). "Antibiotic treatment and cross-fostering experiments demonstrated that the protection against DSS-induced colitis in Prkar2a−/− mice was largely dependent on the gut microflora." (PMID 34349238, 2021). "Altogether, our work demonstrates a previously unidentified function of PRKAR2A in promoting DSS-induced colitis." (PMID 34349238, 2021). "Collectively, our results indicate that IECs contribute to the protection against DSS-induced colitis in Prkar2a−/− mice." (PMID 34349238, 2021). "Global knockout of PRKAR2A alleviated DSS-induced colitis by promoting type I IFN-stimulated gene (ISG) expression and modulating gut microbial composition." (PMID 34349238, 2021). "To assess the possible contribution of ISGs to the amelioration of DSS-induced colitis in Prkar2a−/− mice, we used trichostatin A (TSA) to inhibit ISGs." (PMID 34349238, 2021). "To elucidate the potential pathways involved in the protection against DSS-induced colitis after PRKAR2A ablation, we performed whole-transcriptome analysis of colon tissues from WT and Prkar2a−/− mice using RNA sequencing (RNA-seq)." (PMID 34349238, 2021). "Our cross-fostering experiments further confirmed that gut microbiota primarily contributed to the ameliorated colitis in Prkar2a−/− mice." (PMID 34349238, 2021). "Interestingly, although Prkar2a−/− mice exhibited an ameliorated DSS-induced colitis, STAT3 activation decreased in Prkar2a−/− mice than in WT mice during acute colitis." (PMID 34349238, 2021). "However, the severity of colitis in TSA-treated Prkar2a−/− mice was still milder than that in WT mice, suggesting that ISGs inhibition cannot completely reverse the resistance to DSS-induced colitis in Prkar2a−/− mice." (PMID 34349238, 2021).
colitis (continued). "After treatment with broad-spectrum antibiotics, Prkar2a deficiency failed to protect mice from DSS-induced colitis, as indicated by comparable weight loss, histological score, and colon length in WT and Prkar2a−/− mice." (PMID 34349238, 2021). "Collectively, our data suggest that PKA activation is an early event in experimental colitis, and the disassociated PRKAR2A after PKA activation might take part in the subsequent STAT3 activation, but it is not dependent on the classical IL-6 signaling." (PMID 34349238, 2021). "In summary, our results indicated that the amelioration of colitis in Prkar2a−/− mice was partly due to elevated ISGs, and other unknown mechanisms might exist that contribute to the protection against colitis in Prkar2a−/− mice." (PMID 34349238, 2021). "Therefore, we conducted this study to investigate the role of the PKA regulatory subunit PRKAR2A in colitis." (PMID 34349238, 2021). "These researches suggest that the reduced abundance of Bacteroides and Blautia in Prkar2a−/− mice after DSS treatment might contribute to the amelioration of colitis." (PMID 34349238, 2021). "However, PKA was activated at an early time point, as demonstrated by p-PRKAR2A, which was downregulated on day 3 of colitis." (PMID 34349238, 2021). "Interestingly, although the abundance of Blautia in Prkar2a−/− mice decreased during colitis, the relative abundance of Blautia was higher in Prkar2a−/− mice than in WT mice at the steady state." (PMID 34349238, 2021). "Indeed, little difference was observed in the severity of DSS-induced colitis between WT and Prkar2a−/− mice after eliminating the gut bacteria with antibiotics." (PMID 34349238, 2021). "To verify whether an altered microbiota contributes to the ameliorated colitis in Prkar2a−/− mice, we treated WT and Prkar2a−/− mice with drinking water containing a broad-spectrum antibiotic cocktail for 4 weeks to eliminate the gut luminal bacteria before DSS administration." (PMID 34349238, 2021). "Therefore, we conducted this study to investigate the role of PRKAR2A in colitis." (PMID 34349238, 2021). "Likewise, our investigation also showed that the Wnt/β‐catenin signalling was essential to the malignant transformation of colitis, and PRKAR2A‐derived circRNAs could significantly promote the colitis‐to‐CAC transition by activating the canonical Wnt signalling pathway." (PMID 37138536, 2023). "In this study, we demonstrated that PRKAR2A phosphorylation (p-PRKAR2A) was decreased in colonic mucosal of patients with UC and in mice with dextran sulfate sodium (DSS)-induced colitis." (PMID 34349238, 2021). "Taken together, our data reveal that p-PRKAR2A is downregulated in patients with UC and mice with DSS-induced colitis." (PMID 34349238, 2021). "However, three PRKAR2A‐derived circRNAs, which had high RNA similarities of mmu_circ_0001845, were remarkably up‐regulated in CAC tissues and promoted the colitis to CAC transition." (PMID 35184406, 2022). "Moreover, Prkar2a−/− mice exhibited less abundance of the genera Bacteroides and Blautia, as compared to WT controls during DSS-induced colitis development." (PMID 34349238, 2021). "After challenging with DSS, TSA-treated Prkar2a−/− mice showed exacerbated colitis as compared to non-TSA-treated Prkar2a−/− mice, as assessed by an accelerated weight loss, higher histological score, and severe colon shortening." (PMID 34349238, 2021). "Prkar2a−/− mice were cross-fostered with WT mothers at birth (CF-Prkar2a−/−), and they exhibited severe colitis as compared to non-CF Prkar2a−/− mice." (PMID 34349238, 2021). "Taken together, our results suggest that the absence of PRKAR2A protects mice from DSS-induced colitis." (PMID 34349238, 2021).
colitis (continued). "The percentage of MUC2+ goblet cells was comparable in WT and Prkar2a−/− mice at the steady state, while during DSS-induced colitis, the number of MUC2+ goblet cells in Prkar2a−/− mice was higher than that in WT mice, suggesting a lower goblet cell loss in Prkar2a−/− mice during colon inflammation." (PMID 34349238, 2021). "In contrast, newborn WT mice cross-fostered with Prkar2a−/− mothers (CF-WT) developed milder colitis as compared to non-CF WT mice." (PMID 34349238, 2021). "As STAT3 activation was suppressed in Prkar2a−/− mice and PKA was activated before STAT3 during colitis, we hypothesized that PRKAR2A might influence experimental colitis by modulating STAT3 signaling." (PMID 34349238, 2021). "Taken together, our results suggest that Prkar2a ablation in myeloid cells does not protect the mice against DSS-induced colitis." (PMID 34349238, 2021). "However, three PRKAR2A‐derived circRNAs, which had the high RNA similarities to mmu_circ_0001845, were remarkably up‐regulated in CAC tissue samples and promoted the transition from colitis to CAC." (PMID 35184406, 2022). "By RNA blasting between mice and humans, the RTEL1‐ and PRKAR2A‐derived circRNAs were identified, and the data showed that RTEL1‐derived circRNAs had no clinical significance in human colitis and CAC." (PMID 35184406, 2022).
Parkinson disease (3 papers, 2016 to 2023). A progressive degenerative disorder of the central nervous system characterized by loss of dopamine producing neurons in the substantia nigra and the presence of Lewy bodies in the substantia nigra and locus coeruleus. "Therefore, it is plausible that the differential phosphorylation of the perturbators of this protein, PRKACA, PRKAR2A, and PRKAR2B, produces its downregulation and may trigger Parkinsonism." (PMID 34066091, 2021).
breast carcinoma (2 papers, 2015 to 2021). "There is a report of a single in-frame expressed fusion gene resulting from a chromosomal translocation in breast cancer between PRKAR2A and SLC26A6, which encodes an anion transporter, but the oncogenetic significance of this event has not been determined." (PMID 26608815, 2015).
colorectal cancer (2 papers, 2021 to 2022). A primary or metastatic malignant neoplasm that affects the colon or rectum. "To confirm these results, we stably knocked down PRKAR2A through lentiviral transduction of short hairpin RNA (shRNA) in the human colorectal cancer cell line SW480." (PMID 34349238, 2021). "To determine whether PRKAR2A regulates STAT3 activation through IL-6, we transiently transfected human colorectal cancer cell line RKO with specific PRKAR2A small interfering RNA (siRNA) or control siRNA, and a clear knockdown of PRKAR2A was achieved." (PMID 34349238, 2021).
depression (2 papers, 2023 to 2025). "Moreover, among the 18 depression causal genes with sex-biased protein expression that we identified, GGH and PRKAR2A are implicated in immune response." (PMID 37653343, 2023). "These clusters particularly involved genes related to regulatory subunits of cAMP-dependent protein kinases, such as PRKAR2A, cAMP-responsive element-binding pathway, circadian rhythms, such as CLOCK, ARNT1, CRY2, PER1, and PER2, and anxiety and depression, such as NOTCH1, NOTCH2 and ANK2." (PMID 41157308, 2025).
fibrolamellar carcinoma (2 papers, 2023 to 2024). "In the first dataset (GSE215785), common fibrolamellar carcinoma mutant backgrounds were generated, including BAP1 single-knockout and BAP1/PRKAR2A double-knockout organoids." (PMID 39554490, 2024).
lung adenocarcinoma (2 papers, 2013 to 2022). A carcinoma that arises from the lung and is characterized by the presence of malignant glandular epithelial cells. "One of the important factors in GPCR signaling is the regulatory subunit of PKA named PRKAR2A, which is overexpressed in lung adenocarcinoma." (PMID 23874428, 2013).
Obesity (2 papers, 2020 to 2023). Accumulation of substantial excess body fat. "Global knockout of the PKA regulatory subunits RIIβ (Prkar2b), RIIα (Prkar2a), and the catalytic subunit beta (Prkacb) in mice all caused distinct forms of diet-induced obesity resistance that conveyed a range of sex-dependent phenotypic characteristics." (PMID 38027204, 2023). "Additionally, disruption of either of the PKA type II regulatory subunits, Prkar2b and Prkar2a, known for their interactions with AKAPs, cause resistance to diet-induced obesity in mice (by different mechanisms)." (PMID 38027204, 2023). "In mice, deletion of Prkar2a led to a diet-induced obesity–resistant (DIO-resistant) phenotype and improved glucose tolerance after chronic high-fat diet (HFD) feeding." (PMID 33141766, 2020). "We identify habenular Prkar2a as a new player in regulating the habenular complex (aka, dorsal diencephalic conduction system) and provide new insights into the role of habenular PKA signaling, the regulation of hedonic drive, and susceptibility to dietary obesity." (PMID 33141766, 2020).
colon cancer (1 paper, 2022). "Similar to the activated role of mmu_circ_0001845 in murine colon cancer cells, the results of FOP/FOP flash also confirmed that human PRKAR2A‐derived circRNAs could significantly activate the Wnt signalling in CRC cells." (PMID 35184406, 2022).
diffuse large B-cell lymphoma (1 paper, 2015). "Both Prkar2a−/− and Prkar2a+/− mice frequently developed hematopoietic neoplasms dominated by histiocytic sarcomas (HS) with rare diffuse large B cell lymphomas (DLBCL)." (PMID 26608815, 2015).
glioblastoma (1 paper, 2021). The most malignant astrocytic tumor (WHO grade IV). "We also explored the correlation between the expression of PRKAR2A and other genes in glioblastoma tissue database: interestingly, PRKAR2A correlated with Golgin genes linked to vesicular membrane trafficking, and the R2-binding AKAP12." (PMID 34372567, 2021). "Next, we interrogated the TCGA database, which reports data from 172 glioblastoma specimens, for possible correlations between the expression of PRKAR2A gene, which codes for R2A, and other selected genes." (PMID 34372567, 2021).
histiocytic sarcoma (1 paper, 2015). An aggressive malignant neoplasm with a poor response to therapy, usually presenting as stage III/IV disease. "Remarkably, a total of 16 cases (51.6 %), including 11/19 cases from the Prkar2a+/− mice (58 %), were diagnosed as histiocytic sarcomas (HS)." (PMID 26608815, 2015).
Lymphadenopathy (1 paper, 2015). Enlargement (swelling) of a lymph node. "Prkar1a+/−, Prkar2a+/−, Prkar2a−/−, Prkar2b+/− and wild type (WT) mice were necropsied when they developed splenomegaly, lymphadenopathy (at any age) or when moribund between 5 and 25 months of age." (PMID 26608815, 2015).
meningioma (1 paper, 2019). A generally slow growing tumor attached to the dura mater. "Next, a database reporting the expression level of different genes in 68 meningioma cases was interrogated with BioGPS to explore the relationship between PRKACA gene, coding for PKA CAT, and PKA regulatory subunits (PRKAR1A, PRKAR1B, PRKAR2A, and PRKAR2B) gene products." (PMID 31671850, 2019).
ovarian carcinoma (1 paper, 2017). A malignant neoplasm originating from the surface ovarian epithelium. "PRKAR2A-rearrangements have been reported as an in-frame CDC25A-PRKAR2A fusion in the TCGA ovarian cancer data set." (PMID 28893231, 2017).
Sepsis (1 paper, 2023). Sepsis is defined as life-threatening organ dysfunction caused by a dysregulated host response to infection. "In our investigation, we identified GTPBP2, ALDOA, PRKAR2A, NHLRC2, and KIF2C as genes related to sepsis death using three distinct techniques." (PMID 38054005, 2023). "In our study, we constructed a machine learning model using five genes, including GTPBP2, ALDOA, PRKAR2A, KIF2C, and NHLRC2, to identify sepsis patients with a poor prognosis." (PMID 38054005, 2023).